DEFB105B (defensin beta 105B)
Description:
Has antibacterial activity.
Synonyms: BD-5; DEFB-5
Gene: Protein-coding gene on chromosome 8 (7,487,679 to 7,489,593, forward strand). Ensembl gene ENSG00000186599.
Subcellular location: Secreted
Pathways (Reactome):
Immune System: Beta defensins; Defensins
Gene Ontology:
Biological process: innate immune response
Cellular component: extracellular region
Homologues: Orthologues: chimpanzee DEFB105A (96% identical), dog DEFB105A (68% identical), rat Defb105a (68% identical), rat Defb105b (68% identical), mouse Defb12 (67% identical), dog DEFB105A (60% identical), mouse Defb35 (46% identical). Paralogues in human: DEFB105A (100% identical).